TNF (tumor necrosis factor)
Diseases named in the same sentence as TNF in open-access papers (continued):
Sharing a sentence is not in itself a finding about the gene and the disease.
Stroke (continued). "At 4 h post-stroke, which represents the acute phase of the neuro-inflammatory response and is primarily driven by brain-resident microglia, mRNA expression of TNFα was elevated in peri-infarct brain tissue of both saline- and clenbuterol-treated mice relative to sham mice." (PMID 31138227, 2019). "To test whether naloxone enantiomers affect cytokine secretion, we isolated CD11b+ microglia/macrophages from the infarct area at day 7 post-stroke and measured the secretion of TNF-α, a cytokine with well-characterized pro-inflammatory effects downstream of TLR4 signaling." (PMID 29766045, 2018). "Inflammation, which could drive the progress of cardiovascular diseases, could also be regulated by vitamin D. Vitamin D could inhibit the production of inflammation factors, such as interleukin 6 (IL-6) and tumor necrosis factor alpha (TNF-α), and as a result affect the progress of stroke." (PMID 29495586, 2018). "Furthermore, we showed that steppogenin suppressed inducible NF-kB activation and the subsequent induction of proinflammatory mediators, such as NO, PGE2, IL-1β, IL-6, TNF-α, IL-12 and that it blocked the neuronal disorders including Alzheimer’s disease, Parkinson’s disease, and stroke." (PMID 29207498, 2017). "Furthermore, other groups have reported heightened ADAM17 activity in animal models of ischemic brain injury, as well as stroke-induced increases in peripherally circulating levels of other ADAM17 substrates such as tumor necrosis factor alpha (TNFα) in human subjects." (PMID 29021532, 2017). "After stroke, necrotic lesion produces abundant damage-associated molecular patterns (DAMPs), such as mitochondrial DNA, ATP, and carboxyalkylpyrroles, to which injured brain cells exposed secret inflammation mediators, such as platelet-activating factor (PAF), TNF-α and IL-1β, and chemokines." (PMID 27688603, 2016). "Importantly, IL1A, ILAB, IL6 and TNF and other anti-stroke target genes were up-regulated in males." (PMID 27672514, 2016). "TNF may also play a role in influencing outcome after a stroke." (PMID 26749043, 2016). "A growing body of evidence indicates that TNF-α may play a role in the regulation of tolerance to chronic hypoxia such as occurs in ischemia yet it has a deleterious effect in ischemic brain injury after stroke." (PMID 26901230, 2016). "Importantly, it was found that TNF-α levels are increased in CSF of stroke patients." (PMID 26491692, 2015). "LPS preconditioning significantly increased the level of TNF-α in blood prior to stroke, and TNF-α-deficient mice could not generate a protective effect of cerebral ischemia induced by LPS preconditioning." (PMID 25928750, 2015). "TNF, IL-1 and IL-6 strongly affect the development of ischemic brain damage in animal models, and their levels are increased in the blood and in the cerebrospinal fluid of stroke patients, thus attracting considerable interest as putative markers of stroke severity and neurologic outcome." (PMID 25972779, 2015). "Moreover, TNF-α plasma levels correlated with infarct volume and with stroke outcome." (PMID 25086655, 2014). "The T-P network of anti-stroke herbs constructed in our work demonstrates that herbal medicines might simultaneously target several pathways like PI3K-Akt, TNF and calcium signaling pathways, and thereby exhibit synergistic benefits in stroke treatment and prevention." (PMID 25093322, 2014). "Because white blood cell (WBC) count, hsCRP, TNFα, and IL-6 are reported to be independent parameters predicting stroke outcomes, we are interested in whether leukocyte ROCK activity correlates with these inflammatory cytokines in acute ischemic stroke patients." (PMID 24716192, 2014). "Because TNF-α was shown to promote ADAMTS-1 and -4 mRNA levels as well as ADAMTS-4 and -5 protein levels in human astrocyte cultures, it was hypothesized that the increase of TNF-α expression in the acute phase of stroke may be responsible for the upregulation of ADAMTS-1 and -4 by astrocytes." (PMID 24176075, 2013).
Stroke (continued). "Expression of TNF-α during the critical period of a stroke may restrict aggressive immune responses because the TNF signaling pathway involving CD95-CD95L (ligand) interactions is considered to be the controlling mechanism of T cell expansion during the immune response." (PMID 21450100, 2011). "However, as with IL-6, TNF-α has also demonstrated neuroprotective effects in cerebral injury and could be related to the different stages of stroke pathogenesis." (PMID 22132330, 2011). "Compounds that directly induce expression of A2A receptors on neutrophils such as LPS, or those that elicit the release of cytokines like TNF-α, Interleukin 1β (IL-1β), may be useful as prophylactic neuroprotectants by reprogramming the response of neutrophils to stroke." (PMID 20190963, 2009). "Understanding how adenosine modulates the release of TNF-α by both peripheral immune cells and by cells in the CNS may be particularly beneficial when developing adenosine based therapies for the treatment of stroke." (PMID 20190963, 2009). "Cytokines such as interleukin(IL)-1, tumour necrosis factor-α (TNF-α) and IL-6 appear to be crucial mediators of such responses, yet much remains unknown about their complex interactions in the setting of clinical stroke." (PMID 17328808, 2007). "The simulation of IL-10 bolus and TNF-α blockade exemplifies how predictive modeling may anticipate unintended immunological trade-offs, information that is critical given the failure of some clinical anti-cytokine therapies to demonstrate efficacy in stroke trials." (PMID 41557608, 2026). "A large body of preclinical research has confirmed that in experimental stroke models, VNS can significantly reduce infarct volume, lower the levels of pro-inflammatory cytokines (e.g., TNF-α, IL-6) in serum and brain tissue, and improve neurological outcomes." (PMID 41601622, 2026). "Meanwhile, in stroke animals, this compound significantly decreased the circulating IL1-β, TNF-α and IFN-γ levels." (PMID 39859444, 2025). "Local and systemic inflammatory responses, characterized by elevated levels of tumor necrosis factor-alpha (TNF-α) and interleukin-6 (IL-6), have been well-established in post-stroke patients." (PMID 39745590, 2025). "Our RNA-seq results showed that differential genes were enriched in the MAPK, TNF, and IL-17 signaling pathways, suggesting that LIPUS improves the inflammatory state after stroke." (PMID 40290135, 2025). "In contrast, anti-TNF-α drugs significantly reduced BBB destruction and improved outcomes after the stroke." (PMID 40867580, 2025). "Compared to conventional treatment, the Tongxinluo group showed significant improvements in TC, TG, LDL-C, HDL-C, TNF-α, and hs-CRP levels in stroke patients." (PMID 40761406, 2025). "pronounced elevations in IL-1β, IL-6, TNF-α, MCP-1, and IFN-γ at day 1 post-stroke, exacerbated by bacterial injection." (PMID 40581646, 2025). "Compared to conventional treatment, Tongxinluo significantly improves TNF-α, hs-CRP, LDL-C, and TC levels in stroke patients." (PMID 40761406, 2025). "After a stroke, P2X7 receptors on microglia are activated by ATP, triggering the release of IL-1β, IL-18, and TNF-α, promoting apoptosis and contributing to deep ion imbalance during neuronal death." (PMID 40289984, 2025). "Anti‐TNFα treatment notably alleviates BBB disruption and relieves stroke‐induced cerebrovascular injury." (PMID 40682478, 2025). "They exacerbate post‐stroke inflammation by producing inflammatory cytokines such as interferon (IFN)‐γ, interleukin (IL)‐21, tumor necrosis factor (TNF), and IL‐17." (PMID 38323746, 2024). "Inflammatory response was determined by detecting levels of cytokines (interleukin-2 [IL-2], IL-4, IL-5, IL-8, IL-6, IL-10, IL-12p70, IL-17, tumor necrosis factor-α [TNF-α], interferon-γ [IFN-γ], IFN-α, and IL-1β) within 14 days after stroke onset." (PMID 38902691, 2024).
Stroke (continued). "We compared the efficacy of the three treatment outcomes by analyzing the National Institutes of Health Stroke Scale (NIHSS) scores, and the levels of serum inflammatory factors (IL-8, TNF-α, and IL-1β), cone like protein-1 (VILIP-1), and caveolin-1 (Cav-1)." (PMID 38827855, 2024). "The inflammatory cytokines induced by this phenotype, including tumor necrosis factor-alpha (TNF-α), interleukin-1β (IL-1β), and interleukin-6 (IL-6), prolong the inflammatory response and exacerbate brain damage following stroke." (PMID 39639187, 2024). "Levels of TNF-α, TNF-γ, IL-6, MCP-1, and IL-2 were significantly increased at 6 and 22 h after MCAO in mice with stroke injuries." (PMID 39081338, 2024). "Ten eligible studies measuring TNF-alpha were found comprising 742 AIS patients and 629 controls (HC/matched controls: n = 532 stroke mimics: n = 97)." (PMID 39091977, 2024). "An unexpected observation were the comparably lower basal levels of TNF-α and IFN-γ in stroke patients compared to controls." (PMID 39372701, 2024). "They contribute to the exacerbation of post-stroke inflammation by producing inflammatory cytokines like interferon (IFN)-gamma, interleukin (IL)-21, tumor necrosis factor (TNF), and IL-17." (PMID 38894965, 2024). "We reanalyzed plasma IL-1β, IL-6, TNF-α, sICAM-1, sVCAM-1, and FKN levels data obtained in a previous study to test potential differences between HGS stroke patients (within 7 days or 1-year from stroke onset) and healthy controls." (PMID 36536168, 2024). "Kdm6afl/fl mice had significantly higher plasma levels of IL-1β than fl/y mice; whereas Kdm5cfl/fl mice had higher levels of TNF-α than either fl/y and CKO mice after stroke." (PMID 39399684, 2024). "Numerous studies have shown a remarkable elevation in IL-6, TNF, CRP, and neutrophils in patients with stroke." (PMID 38699426, 2024). "In the first 24 hours after stroke, CD4+ Th1 and Th17 cells, as well as γδT and CD8+ cells are the predominant pro-inflammatory T cells, which secrete cytokines such as IL-17, TNF-α, infiltrate the infarcted area." (PMID 39676865, 2024). "Nonetheless, to the authors’ knowledge, this represents the most comprehensive systematic review of blood-based protein biomarkers for stroke: MMP-9, TNF-alpha, VCAM-1, ICAM-1, E-Selectin, P-Selectin, L-Selectin, NSE, GFAP, S100, S100B, BNP, and NT-proBNP." (PMID 39091977, 2024). "We found higher amounts of inflammatory cytokines like TNF- α and IL-6 and chemokine MCP-1 in the plasma of HFD compared to ND stroke mice." (PMID 39845972, 2024). "Compared to ND, HFD increased plasma levels of the proinflammatory cytokines TNF-α, IL-6, IL-23, and MCP-1 in stroke mice." (PMID 39845972, 2024). "Real-time PCR analysis in rats after t-MCAO has revealed that the mRNA levels for TNF-a, IL-1b, IL-6, E-selectin, and ICAM-1 are increased 3 h after stroke that persist for 24 h in the hemisphere ipsilateral to occlusion." (PMID 37342100, 2023). "In T2DM mice, stroke induced earlier and higher TLR4, NLRP3, and cytokine expression (SAA, IL1β, IL6, TNFα) in the liver compared to heart and kidney, as measured by Western blot." (PMID 36968490, 2023). "As important immunological mediators in post-stroke responses, cytokines have been confirmed as independent predictors of SAP, including IL-6, IL-10, and TNFα." (PMID 37065465, 2023). "In stroke, NBP has potential with its dual role; it has arteriogenic effects and the ability to inhibit the expressions of TNF-α and MMP-9." (PMID 37570794, 2023). "We obtained significant distributions of VWF rs61748511 T > C, TNF-alpha rs1800629 G > A and GST rs4025935 and rs71748309 genotypes between stroke cases and the healthy controls (p < 0.05)." (PMID 37240845, 2023). "The present study also revealed the downregulation of the toll-like receptor (TLR) signaling pathway, TNF signaling pathway and NOD-like receptor (NLR) signaling pathway in CD11b+ cells from GSDMD−/− mice with stroke." (PMID 36755018, 2023).
Stroke (continued). "In the present study, there was increased activity of TNF-α, IL-6, and IL-1β in the MCAO-induced animal group indicating the brain injury during the stroke." (PMID 35838888, 2023). "TNF-α secreted by microglia can directly act on TNFR1 on neurons and strongly trigger neuronal death by activating caspase-8 signaling after stroke." (PMID 37486903, 2023). "TNFSF15 belongs to the tumor necrosis factor (TNF) ligand family induced by TNF and IL-1α, which plays an important role under disease conditions, such as cancer and stroke, by maintaining vascular and lymphatic vessel homeostasis." (PMID 36936375, 2023). "In the current study, we examined the associations of the GSTs SNPs (Mu 1 (GSTM1) and Theta 1 (GSTT1)), TNF-alpha SNP rs1800629 G > A SNP and VWF SNP rs61748511 T > C with stroke in the Tabuk population." (PMID 37240845, 2023). "Eriodictyol applied after stroke improves neurological deficits in the MCAO mice model and also decreases infarct volume TNF-α and GFAP expression." (PMID 36901731, 2023). "We identified candidate blood-based protein biomarkers for post-stroke functional outcome involved in, e.g., NLRP3 inflammasome regulation and signaling pathways, such as TNF, JAK/STAT, MAPK, and NF-κB." (PMID 37794467, 2023). "It has been reported that TNF-alpha induces the expression of WBC adhesion molecules, producing oxidative stress, local inflammation, thrombosis and hemorrhage in stroke." (PMID 37240845, 2023). "Stroke patients with metabolic syndrome had increased plasma levels of the proinflammatory cytokines CRP, IL-6 and TNF-α but decreased levels of the anti-inflammatory cytokine IL-10 compared to stroke patients without metabolic syndrome and nonstroke patients." (PMID 37587512, 2023). "Tumor necrosis factor (TNF), a crucial cytokine, has important research value in post-stroke neuroinflammation (PSN)." (PMID 36389810, 2022). "Macrophages/microglia are major source of inflammatory mediators (e.g., TGF-β, IL-6, IL-1β, or TNF-α) in stroke to activate the astrocyte TLR/NF-κB inflammatory pathway and further amplify neuroinflammation to exacerbate neuronal damage and stroke symptoms." (PMID 36159395, 2022). "In an experimental study, administration of tPA aggravates hyperglycemia-induced stroke through upregulation of NLRP3 inflammasome, high mobility box protein 1 (HMGB-1), tumor necrosis factor-alpha (TNF-α) and nuclear factor kappa B (NF-κB)." (PMID 36076264, 2022). "TNF-α/MIP-1α levels significantly decreased, but IL-12p40 significantly increased in IRF5 CKO vs. flox mice after stroke." (PMID 35963621, 2022). "Past studies have demonstrated the inhibition of TNF-α and IL-1β expression via modulation of DAPK1 signaling in stroke." (PMID 36016577, 2022). "Peripheral inflammatory factors, including IL‐1β and TNF‐α, are more likely to aggravate BBB damage and even worsen stroke outcomes." (PMID 35322553, 2022). "Animal studies have shown that the expression of TNF, TNF-related inducing ligand (TRAIL), and Fas ligand (FasL) are all upregulated after ischemia, and these molecules worsen stroke prognosis to some extent." (PMID 35356292, 2022). "Various cytokines such as tumor necrosis factor (TNF), IL-1, and IL-6 are known to regulate the tissue damage in stroke models, and therefore, play a crucial role in poststroke therapies." (PMID 36120593, 2022). "The astrocytes in microglial co-culture have been reported to exhibit A2 phenotype and activated to A1 astrocytes by TNF-α and IFN-γ under the stroke-mimicking condition." (PMID 36159395, 2022). "The current study, therefore, investigated the associations between SNPs of inflammatory molecules, consisting of IL-1β, TNF-α, IL-6, IL-10, IL-18, interferon-γ (IFN-γ) and C-reactive protein (CRP), and PSD at 2 weeks after stroke (early-onset PSD)." (PMID 36225923, 2022).
Stroke (continued). "Our findings have been confirmed by other researchers who believe that IL-6 and TNF-α may be the key inflammatory markers in stroke patients, showing a significant increase in serum levels in numerous studies, within a few hours after the onset of ischemia up to the 90th day after stroke." (PMID 36142524, 2022). "MCAO induced an increase in GM‐CSF and TNF‐α concentrations in the BALF, likely a response to post‐stroke bacterial pneumonia." (PMID 35881080, 2022). "Intraventricular injection of TNFR1 decoy receptors or anti-TNF-α antibodies, as well as systemic injection of TACE inhibitors, can reduce ischemic brain damage in stroke." (PMID 35265224, 2022). "Anti-TNFα treatment significantly ameliorates endothelial necroptosis and BBB destruction and improves stroke outcomes." (PMID 36474712, 2022). "Recent studies suggest beneficial effects of ES in a rat model of stroke, in which mesencephalic electric stimulation attenuated the expression of inflammatory cytokines, IFN-γ, TNF-α, and IL-1α, in the perilesional area of stimulated rats." (PMID 36158207, 2022). "Cytokines, like tumor necrosis factor (TNF), modulate tissue injury in experimental stroke and affect infarct evolution, making them good targets for potential future stroke therapy." (PMID 35694259, 2022). "In trans-well co-cultures of MSCs and monocytes isolated from stroke patients, we found statistically significant increased levels of IL-4 and MCP-1, and decreased levels of IL-6, IL-1β, and TNF-α." (PMID 36277912, 2022). "A positive correlation was found between the concentration of IL-6 and TNF-α in patients with AIS during <4.5 h and on one day after the onset of stroke, which means that the concentration of IL-6 increases with the increase in TNF-α concentration." (PMID 36142524, 2022). "Interleukin-1β (IL-1β), tumor necrosis factor-α (TNF-α) and IL-6, are the main inflammatory factors that trigger and exacerbate the inflammatory response after stroke." (PMID 35281064, 2022). "A correlation was found between TNF-α levels measured during the onset time, with the NIHSS scale on admission, and mRS assessed in the third month after stroke." (PMID 36142524, 2022). "TNF-α antibodies and TNF-α binding proteins have demonstrated efficacy in preclinical stroke models, including MCAo." (PMID 35631536, 2022). "Poncirin suppressed the LPS-induced production of inflammatory cytokines TNF-α and IL-6 in RAW 264.7 macrophages and attenuated ischemic injury in stroke mice." (PMID 36185646, 2022). "Levels of these inflammatory factors, except TNF-α, significantly increased in the ischemic brain in DD/STZ mice at 1 day post-stroke." (PMID 35784349, 2022). "Real-time quantitative PCR measurements suggested the prominent elevation of multiple pro-inflammatory cytokines and chemokines, including IL-1β, IL-6, TNF-α, CCL2, CXCL1, and CXCL10 after stroke." (PMID 35761277, 2022). "The pro-inflammatory cytokines TNF-α and IL1-β were reduced in plasma from stroke animals, whereas anti-inflammatory IL-10 was elevated for 3,6′-DP." (PMID 35631536, 2022). "Lowering but, nevertheless, retaining the early-phase release of TNF-α following a TBI or stroke has been achieved in preclinical animal models of mild and moderate TBI, and stroke by thalidomide analogs." (PMID 33854417, 2021). "In this study, we compared blood TNF, TNFR1, TNFR2, CCL2, and CCR2 levels in stroke patients and healthy controls and investigated the association of TNFR1, TNFR2, CCL2, and CCR2 levels to stroke severity, infarct size, and functional outcome at 90 days." (PMID 33918875, 2021). "TNF-α/IL-10 and IL-6/IL-10 ratio were also significantly higher in NWS and SWS of stroke patients, indicating an intensification of the inflammatory process and a limited anti-inflammatory role of IL-10." (PMID 34433866, 2021). "The core targets of PPI are TNF,IL-6,ALB,AKT1,VEGFA, and CREB1, which play a key role in the regulation of stroke by DZSM." (PMID 34754318, 2021).